COL3A1 (collagen type III alpha 1 chain)
Diseases named in the same sentence as COL3A1 in open-access papers (continued):
Sharing a sentence is not in itself a finding about the gene and the disease.
tumor (continued). "In summary, this present study showed that radiotherapy significantly upregulated the expression of COL1A1, COL3A1, and COL1A2 genes in BCa tumor tissues." (PMID 35274048, 2022). "Among the interactions involved in tumor invasion and growth, extracellular matrix interaction scores were higher between tumor stroma and post-treatment tumor (tumor stroma ligand: COL1A1, COL1A2, and COL3A1; post-treatment tumor receptor: ITGA2)." (PMID 36505794, 2022). "Immune infiltration analysis showed that the expressions levels of COL3A1, RAC1, FN1, and SDC2 in CD4+T cells were significantly higher than those in tumor cells, especially regulatory T cell infiltration was significantly increased in BM tumors." (PMID 34229299, 2021). "We performed differential analysis and correlation analysis of these four genes (COL3A1, COL4A1, COL5A1, and COL15A1) and tumor immune subtypes with tumor microenvironment scores." (PMID 34691289, 2021). "After adjusting the analysis by tumor purity, we found that the expression levels of COL1A2, COL1A1, COL3A1, ZNF469 and Periostin (POSTN) were significantly correlated with tumor purity in ESCA." (PMID 33543230, 2021). "The ECM components COL1A1, COL3A1, COL4A1, and fibronectin 1 (FN1), are critical regulators during tumor metastasis, so we examined their expression in the DCN and control cells using qPCR." (PMID 34504839, 2021). "We found that COL1A2, COL3A1, COL5A2, tumor mediators targeting of relevant structural components of the extracellular matrix (ECM) were activated to drive CAFs to synthetize fibrillar collagen creating an aberrant microenvironment." (PMID 34458147, 2021). "Two studies have identified the potential role of SV2B in promoting tumor metastasis, with MMP9, COL3A1 and SV2B being identified as important hub genes that are associated with ECM–receptor interaction." (PMID 32667033, 2020). "Principal component analysis and random forest analysis were employed to further screen for six hub genes, including ISLR, COL1A2, CDH11, SPARC, COL3A1, and COL1A1, which exhibited a good ability to differentiate between tumor and normal samples." (PMID 32612640, 2020). "COL3A1, COL1A2, COL15A1, ASPN, and MXRA5 were higher expressed in tumor samples, while OGN was lower expressed." (PMID 32300359, 2020). "The quantification results suggested that COL1A1, COL3A1, SPP1, and THBS2 protein levels were significantly increased in GC tumor tissues compared to normal adjacent tissues." (PMID 33665169, 2020). "Gene ontology analysis of these DEGs showed that in advanced stage tumours, pathways such as cell adhesion (VCAN), ECM receptor interaction (COL1A2, COL3A1, ITGA11, and TNN) and pathways in cancer (JUN, and MYC) getting deregulated." (PMID 31292488, 2019). "HK2 gene was significantly and positively correlated with tumor size, whereas PFKFB3 was significantly and positively correlated with COL1A1, COL3A1, and HAS2 genes in TN." (PMID 31428701, 2019). "We first validated expression of COL1A1, COL1A2, and COL3A1, in OSCC fibroblast pairs isolated from tumor or its adjacent stroma, as well as in two OSCC tumor cell lines, CAL27 and HSC-3, using quantitative PCR." (PMID 27128408, 2016). "In this study, we demonstrated the tumor suppressive role of let-7d in RCC and validated that the targets of let-7d were COL3A1, an important stroma component, and CCL7, a chemokine attracting monocytes to tumor tissue." (PMID 25193015, 2014). "Further, we found increased expression of the fibrillar collagen proteins COL3A1 and COL5A1 in muscle-invasive tumor samples and metastatic T24 cells." (PMID 23383328, 2013). "Recently, more reports have shown that miR-29 family regulated tumorigenesis and tumor progression by targeting DNMT3A, DNMT3B, TIAM1, cyclin E, MMP2, ID1, SPARC and COL3A1." (PMID 23936390, 2013).
tumor (continued). "These methods allow for a more granular understanding of gene expression within individual cell types in the tumor and could clarify whether COL3A1, PLAU, and SPP1 are differentially expressed across various cell types within the same tumor." (PMID 41465316, 2025). "Nevertheless, our analysis of the TCGA data has demonstrated that COL3A1 and SPP1 show significant differential expression across AJCC tumor staging, and COL3A1 and PLAU show significant differences in T-staging, while COL3A1 and SPP1 are differentially expressed in N-staging." (PMID 41465316, 2025). "Moreover, we identified five molecules (SCGB1B2P, SFRP2, POSTN, COL3A1, ENTPD6) that were universally overexpressed in medullary cells infiltrated by IBC tumours." (PMID 40624675, 2025). "Conversely, TQ treatment resulted in the downregulation of several genes overexpressed in GBM cells, including potential oncogenes like AEBP1, MIAT, GHR, LMO1, ELF3, and genes involved in tumor proliferation and migration such as EPHA4, COL3A1, PCDH10, ROBO1, ADAMTS5, PCDH18, ST8SIA1." (PMID 39874307, 2025). "Moreover, PECAM1+ cells (ECs) in cluster 8 ECS (COL1A1, COL1A2, COL3A1, PDGFRB, and ACTA2) showed an endothelial-mesenchymal transformation phenotype, which contributed to tumor progression." (PMID 37533434, 2023). "Interestingly, we also anlysized peritoneal metastases from GCPM patients and found that CD93, COL3A1, COL4A1 expression were higher in metastases than in the primary tumor." (PMID 36690975, 2023). "We further found that expression of CD93 was correlated with tumor size, differentiation and peritoneal metastasis; that of COL3A1 was correlated with differentiation, depth of invasion, peritoneal metastasis and TNM stage; that of COL4A1 was correlated with tumor size and peritoneal metastasis." (PMID 36690975, 2023). "This demonstrates that the expression of COL3A1 and GUCA2A can be beneficial as a tumor biomarker." (PMID 37816854, 2023). "Strikingly, examining the source of collagen gene expression (COL1A1, COL1A2, COL3A1, COL6A1, COL8A1, COL10A1) provided clarity that the majority of genes expressed in the tumor samples represent transcripts of the MSC-related component of the tissue microenvironment." (PMID 36940196, 2023). "TGFBI, COL3A1, and CXCL12 were significantly upregulated in caf_C1_scissor, which mainly expressed genes characteristic of activated CAF, which secreted pro-inflammatory factors that enhanced EMT and stemness of tumor cells and contributed to tumor metastasis." (PMID 37091977, 2023). "Furthermore, we also evaluated the expression of myofibroblast marker genes, such as COL1A2, COL3A1, ACTA2, and FAP, in the tumor microenvironment using an IHC assay." (PMID 37953225, 2023). "In summary, lnc-RFNG-1, lnc-TRIM28-14, CD93, COL3A1 and COL4A1 could be novel tumor biomarkers and potential therapeutic targets for GCPM." (PMID 36690975, 2023). "Notably, the expression levels of COL3A1 were reported to be lower among patients with NMIBC and higher among patients with invasive disease, contributing to tumor progression and metastasis." (PMID 35884419, 2022). "On the contrary, we observe upregulated oncogene like COL1A1, COL3A1, and downregulated miRNA, which did not correlate with downregulated collagen in vivo in treated tumour samples (data not shown)." (PMID 35615145, 2022). "On the other hand, COL1A2, COL3A1, COL5A1, FN1, and SPARC may be more involved in tumor progression from stage 1 to stage 2, at which the tumor cells gain the ability to invade surrounding tissues." (PMID 35739492, 2022). "In addition, miR-765 mimics obviously down-regulated the expression of several EMT-related markers (e.g., COL3A1, FN1, CDH2, S100A4, MMP9, SNAIL and ZEB1) and up-regulated TJP1 expression in tumor lesions." (PMID 33859750, 2021). "In addition, gene expression in the primary tumor (T-TIS) was higher compared to control (N-TIS) for most genes (TGFβ1, COL1A1, COL3A1, ITGAV, ITGAX) (matched samples)." (PMID 33718208, 2021).
tumor (continued). "In the frame of type III collagen structure, this data suggests that not all the COL3A1 chains are wrapped to form fibrils and fibers of the tumor ECM scaffold." (PMID 31687002, 2019). "In the 3D organoids, there were noticeable deposits of trichrome stain, Collagen 3A1 (COL3A1), periostin, as they are ECM markers that have been explored in UF, ‐catenin, since it is involved in UF pathogenesis and Oestrogen Receptors (ERα) as this isa hormonal dependent tumour." (PMID 40108998, 2025). "The spatial localization of HYP peptides for COL1A1, COL1A2, COL5A1 and COL3A1 exhibited distinct region-specific patterns in dormant D-HEp3 compared to awakened P4HA2-depleted D-HEp3 cells, suggesting differential regulation of collagen hydroxylation across tumor zones." (PMID 40671813, 2025). "Whether the expression differences were significant was further verified in the TCGA database (Normal,N = 55; Tumor,N = 701), and interestingly, only MFAP4 and COL3A1 were differentially expressed in normal and tumor patients, and the remaining genes were not significantly differentially expressed." (PMID 40061958, 2025). "Differential expression, followed by IPA analysis showed that tumour ROIs were enriched for genes involved in translation elongation and EIF2 signalling, while stroma ROIs were enriched for collagen fibre reorganisation genes, such as COL3A1, and other ECM gene sets." (PMID 38890455, 2024). "We detected 24 genes across the tumor tROIs that showed a high CV (i.e., were among the genes with the top 20% highest CV in seven out of seven cases), such as multiple collagens (COL1A1, COL1A2, COL3A1, COL5A1, COL5A2), S100A8, S100A9, FN1, or Early growth response protein 1 (EGR1)." (PMID 37511126, 2023). "Moreover, other genes such as TLR4, CD4, COL3A1, and ITGB3 are also of great research value, and whether other genes are also involved in the regulation of tumor bone metastases will be investigated in the later studies." (PMID 37007939, 2023). "Although no study indicated COL3A1 regulated propanoate metabolism, we speculated COL3A1 down‐regulated propanoate metabolism to promote lipogenesis, thus promoting angiogenesis in tumour genesis and recurrence." (PMID 32757451, 2020). "Interestingly, the coefficient of alignment specifically measured for COL3A1 showed a similar score to the total collagen fibers, thus suggesting the involvement of the type III collagen in the ECM re-organization during tumor progression." (PMID 31687002, 2019). "In summary, our results indicate that the tumor suppression role of let-7d in RCC may be partially ascribed to its ability to decrease collagen expression and macrophage recruitment through targeting COL3A1 and CCL7 mRNAs." (PMID 25193015, 2014). "While increased expression of ECM-related genes like COL3A1, PLAU, and SPP1 may initially contribute to tumor growth, invasion, and metastasis by promoting ECM remodeling and cell migration, their downregulation later in tumor progression might reflect a more aggressive, metastatic phenotype." (PMID 41465316, 2025). "In ROC analyses, COL5A2 exhibited stable tumor-versus-non-tumor discrimination across GSE15471, GSE16515, and GSE62452 (AUC = 0.932, 0.760, and 0.782, respectively) and significantly outperformed COL3A1 in two cohorts." (PMID 42072830, 2026). "And transcriptional data reveal that compared to the adjacent non-tumorous samples, expression of COL3A1, COL1A2, FBN1, IGFBP7, and FSTL1 was significantly elevated in the tumor tissue." (PMID 38478111, 2024). "For non-immune cell populations, we identified tumor cells (EPCAM and CLDN4), fibroblasts (COL3A1 and NNMT), and mesothelial cells (LRRN4 and WT1)." (PMID 36788228, 2023). "Besides, we found three genes, including COL1A1, COL3A1, and COL1A2, were significantly upregulated in TCGA BRCA tumor samples compared with normal controls, whereas the other seven genes were not significantly changed in BCa tumor samples (data now shown)." (PMID 35274048, 2022).
cancer (130 papers, 2010 to 2025). A tumor composed of atypical neoplastic, often pleomorphic cells that invade other tissues. "Module III is enriched with genes of cancer-associated fibroblasts (CAFs) like COL1A1, COL1A2, and COL3A1, distributing spatially around cancer cells for tumorigenesis promotion." (PMID 40033360, 2025). "In metastatic LNs, most ligand‒receptor pairs are related to the collagen family, which includes genes such as COL1A1, COL1A2, and COL3A1, which are markers of cancer‐associated fibroblasts (CAFs)." (PMID 39312471, 2024). "High levels of COL3A1 is associated with poor prognosis of the cancer patient because it promotes cell viability and inhibits apoptosis." (PMID 38304289, 2023). "Fibro_2 cells were characterized by collagen (COL1A1, COL3A1) and cancer-associated fibroblast genes (CTHRC1, FAP)." (PMID 35935940, 2022). "Overexpression of COL3A1 mRNA in 435 cell lines was linked to higher sensitivity to four anti-cancer drugs, including the ATM kinase inhibitor KU55933 (r = − 0.599)." (PMID 33766047, 2021). "Many important components of ECM, which were differentially expressed in cluster 1 or 2, such as COL6A1, COL1A1, and COL3A1, are mainly secreted by cancer-associated fibroblasts (CAF)." (PMID 33508502, 2021). "COL3A1 encodes fibrillar collagen, a major component of the extracellular matrix protein surrounding cancer cells." (PMID 28191466, 2017). "COL3A1 was found to be upregulated in several cancers, and was revealed to be a candidate diagnostic marker for mesothelioma." (PMID 26741506, 2016). "Collagen alpha-1(III) (COL3A1) gene, encoding an extracellular matrix protein, is upregulated in human cancers." (PMID 26741506, 2016). "COL3A1 encodes a fibrillar collagen which is a major component of the extracellular matrix protein surrounding cancer cells." (PMID 21114830, 2010). "COL3A1 demonstrated a positive correlation with M2 macrophages and cancer-associated fibroblasts." (PMID 38610959, 2024). "Interestingly, the increased COL3A1 protein in cancer epithelial region was significantly associated with poor OS revealed by the Kaplan-Meier analysis (LRT, p = 0.03)." (PMID 26741506, 2016). "The highest expression of genes encoding Col1a1-2, Col3a1, Col4a1, Col4a2, Col5a1, Col5a2, Col6a1, Col8a1, Col9a3, Col10a1, Col12a1, Col14a1, Col15a1, Col16a1, Col18a1, and Col28a1 were detected in untreated tumors, whose landscapes were dominated by Krt8+ cancer cells." (PMID 39372930, 2024). "However, except for COL3A1, the NK-inhibitory ligands were associated with favorable prognosis, suggesting that these ligands might have a cancer-protective role in addition to their function as NK-inhibitory ligands." (PMID 29930758, 2018). "The model genes exhibited strong positive correlations with both immune scores and stromal scores across the majority of cancers, and COL3A1 was significantly correlated with elevated immune scores and increased stromal scores in CHOL." (PMID 40433364, 2025). "We identified a population of cancer-associated fibroblasts (CAFs), marked by the expression of genes such as COL1A1, COL3A1, COL11A1, and ACTA2, which are known to contribute to the activation of EMT programing." (PMID 40950184, 2025). "Earlier studies have also reported the association of COL1A1, COL1A2, COL3A1, and FN1 expression with OS in different other cancer patients." (PMID 38913913, 2024). "The most marked cluster comprised of collagen genes associated with tissue remodelling (COL1A1, COL3A1 and COL6A3); these show steady increase in expression across normal, inflamed, dysplastic and cancer tissue." (PMID 38505585, 2024).
cancer (continued). "In the “transition zone”, fibroblasts were mapped to the center of the small sample, clearly distinguishing the cancer and normal areas, aligning with the distribution of its marker gene COL3A1." (PMID 38672453, 2024). "In the future, more validation methods should be performed to verify the importance of these EMP1+/COL3A1+ fibroblasts during the BoM process in more types of cancers." (PMID 38187400, 2023). "Patients with high percentage of cancer associated fibroblasts and expression of TIMP3 but low expression of COL1A1, COL3A1, MMP1 and POSTN were associated with sensitivity to paclitaxel." (PMID 35480306, 2022). "In contrast, for patients with lower number of NART responses, we observed high expression of FN1, ITGA5 and COL3A1, which is correlated with poor survival for cancer patients." (PMID 35410325, 2022). "Based on the TCGA-LUSC cohort, a high percentage of cancer associated fibroblasts and COL1A1, COL3A1, POSTN1 and TIMP3 expression was also associated with resistance to immunotherapy." (PMID 35480306, 2022). "We found genes related to extracellular matrix organization, such as SPP1, MT1L, and COL3A1 (among others), which functioned as NET-associated regulatory genes exclusively in cancer types with poor NET-related survival." (PMID 35432310, 2022). "Let-7d directly targets c-Myc, HMGA2, CCL7, PBX3 and COL3A1, and so inhibits thereby inhibiting cancer cell invasion and metastasis." (PMID 33507713, 2021). "Genes such as COL1A1 and COL3A1, components of collagen fibril are extracellular matrix structural constituent and play important role in cancer invasion and metastasis." (PMID 33663405, 2021). "It has been reported that overexpression of COL3A1 is correlated with worse prognosis in many cancers." (PMID 33766047, 2021). "From the gene expression results, we observed that the amount of COL1A1 increased in cancer tissue compared to COL3A1." (PMID 34771715, 2021). "COL3A1 was present not only as a cellular protein inside the cancer cells but also in cell culture medium as a secreted protein." (PMID 33921897, 2021). "For the data set of OV, 67 genes were identified by univariate Cox regression to be significantly associated with the cancer and seven of them, namely COL1A1, COL3A1, RPL10, ARHGAP5, LATS1, TSHR and SLC34A2, were found in the CGC data set." (PMID 32429941, 2020). "Although type III collagen role in ECM organization and function is still poorly, recent evidences indicated a clear role of COL3A1 in promoting the progression of invasive solid cancers and its involvement in the tumorigenesis of many cancers type." (PMID 31687002, 2019). "In consistent with the mRNA expression, COL3A1 protein was significantly upregulated in cancer epithelial tissues comparing with the normal tissues (unpaired Student's t test, p = 3.4E-33, n = 84, or paired Student's t test, p = 4.6E-22, n = 76)." (PMID 26741506, 2016). "COL3A1 was expressed in cytoplasm and nucleus and its expression in cancer epithelial and stromal region varied." (PMID 26741506, 2016). "It was intriguing that COL3A1 protein localized on nucleus of cancer epithelial cells, in addition to the cytoplasm and extracellular space." (PMID 26741506, 2016). "Kaplan-Meier survival analysis revealed that increased COL3A1 protein in cancer epithelial cells predicted worse prognosis." (PMID 26741506, 2016). "We further analyzed COL3A1 silencing in vivo using a zebra fish xenograft model, which has been used in cancer proliferation, cell invasion and metastasis analyses." (PMID 26741506, 2016). "In younger (age < 60) or older (age ≥ 60) individuals, plasma COL3A1 was significantly higher in the cancer group than the healthy group." (PMID 26741506, 2016). "Some of these cancer-related genes were associated with processes occurring in the extracellular matrix and related to DCN: CXCR4/CXCL12 axis, SELP, vWF, COL3A1, SCARA, SPARCL1." (PMID 26437222, 2015).